CD44 (CD44 molecule (IN blood group))
Diseases named in the same sentence as CD44 in open-access papers (continued):
Sharing a sentence is not in itself a finding about the gene and the disease.
papillary thyroid carcinoma (10 papers, 2010 to 2023). "Positive immunoexpression of CK-19, Galectin-3, HBME-1, and CD-44 improves the diagnostic accuracy of papillary thyroid cancer." (PMID 21052476, 2010). "In thyroid tumors, including papillary thyroid carcinoma, CD44 resulted the best marker for the identification of thyroid stem cells, that also expressed POU5F1." (PMID 34219203, 2021). "CD44 immunostaining showed that 24 out of 39 papillary thyroid carcinoma tissues have a high positive expression of CD44 (P=0.003)." (PMID 31341476, 2019). "Other studies showed that most papillary carcinomas express CD44 and cyclin D1, whereas it is less common in follicular neoplasm and nodular goiter, suggesting that could be helpful in diagnostically difficult cases." (PMID 31341476, 2019). "Furthermore, at that time, it was recognized that most thyroid papillary carcinomas express CD44, and it was suggested to have clinical value in confirming the diagnosis of malignancy when fine‐needle aspiration specimens were used." (PMID 31341476, 2019). "Approximately 38.5% of papillary thyroid carcinoma tissues showed low CD44 expression." (PMID 31341476, 2019). "According to recent research, several diagnostic and prognostic markers have been proposed in improving the diagnostic accuracy of papillary thyroid cancer such as Cytokeratin-19 (CK-19), HBME-1, Galectin-3, CD44, CD56, E-cadherin, c-erbB-2, p21cip1, p27kip1, and p16ink4a." (PMID 21052476, 2010). "As our results showed, expression levels of ALDH1A1, CD44, OCT3/4, and ABCG2 genes were relevant to papillary thyroid cancer stages starting from stage I to stage III, whereas in the benign tumor it was not." (PMID 31341476, 2019). "In this study, we found that CK-19, Galectin-3, CD-44, and HBME1 were highly expressed in papillary carcinomas, a finding that is in agreement with other data reported in the literature." (PMID 21052476, 2010).
colorectal adenocarcinoma (9 papers, 2012 to 2025). The most common type of colorectal carcinoma. "Choi and collaborators observed an association between CD44 expression and tumour size studding colorectal adenocarcinoma." (PMID 23419168, 2013). "In colorectal adenocarcinoma, OPN mostly located at the tumor budding and invasion front and colocalized with CAFs and TAMs adjacent to CD44+ colorectal adenocarcinoma cells, a defining feature for colorectal adenocarcinoma prognosis." (PMID 40865052, 2025). "The HT-29 cellline (human colorectal adenocarcinoma) and HT-29 CSCs (HT-29 CD133+/CD44+ cells) were cultured for 72 h." (PMID 37636966, 2023). "HT29 human colorectal adenocarcinoma xenograft showed similar results to the C26 isograft, while both HT25 and HCT116 behaved differently, which proposed further explanation to the contradictions of CD44 literature." (PMID 23151220, 2012).
non-Hodgkin lymphoma (9 papers, 2010 to 2024). Distinct from Hodgkin lymphoma both morphologically and biologically, non-Hodgkin lymphoma (NHL) is characterized by the absence of Reed-Sternberg cells, can occur at any age, and usually presents as a localized or generalized lymphadenopathy associated with fever and weight loss. "Elevated serum CD44, a transmembrane glycoprotein involving lymphocyte activation, adhesion, and migration, was correlated with the prognosis outcome in human non-Hodgkin lymphoma." (PMID 35765478, 2022). "CD44 is epigenetically regulated in Hodgkin and non-Hodgkin lymphomas and is reported to be unmethylated in the L-1236 cell line." (PMID 30857150, 2019). "The median serum level of CD44 in non-Hodgkin lymphomas was 540 ng/mL91." (PMID 34599251, 2021).
small cell lung carcinoma (9 papers, 2010 to 2025). Small cell lung cancer (SCLC) is a highly aggressive malignant neoplasm, accounting for 10-15% of lung cancer cases, characterized byrapid growth, and early metastasis. "CD44+ CD90+ CSCs have a higher tendency for lymph node metastasis in small-cell lung cancer (SCLC), which promotes the response of cytotoxic T lymphocytes (CTLs)." (PMID 38164743, 2023). "A report on small cell lung cancers showed that activation of CD44-MAPK-PI3K signaling led to increased expression of uPA/uPAR and MDR1, resulting in enhanced invasive and multi-drug resistant cancer phenotypes." (PMID 21124918, 2010). "In small cell lung cancers, it was shown that activation of CD44-MAPK-PI3K signalling results in the increased expression of urokinase plasminogen activator and its receptor, uPAR, and MDR1, resulting in enhanced invasive and multi-drug resistant cancer phenotypes." (PMID 23349823, 2013). "However, staining for CD44 or splice variants such as CD44v6 were often found to be negative in small cell lung cancer." (PMID 24699516, 2014). "Inhibition of PFKFB3 by the glycolytic inhibitor PFK158 and by shRNA stable knockdown in small cell lung carcinoma (SCLC) cell lines inhibited glycolysis, proliferation, spheroid formation, and the expression of cancer stem cell markers CD133, Aldh1, CD44, Sox2, and ABCG2." (PMID 35804016, 2022).
squamous cell lung carcinoma (9 papers, 2021 to 2026). A carcinoma arising from squamous bronchial epithelial cells. "Other researchers observed that an active CD44/p-AKT/AKT signaling pathway promotes resistance to FGFR1 inhibition in squamous-cell lung cancer." (PMID 40558504, 2025). "CD44/PAK1/AKT activation may help predict the response to FGFR1 inhibition in squamous cell lung cancer." (PMID 41459112, 2026). "CD44 and ALDH co-expressing cells, which are higher in lung squamous cell carcinoma, always show increased self-renewal capacity, enhanced migration ability, and tumorigenicity." (PMID 35719973, 2022).
Autoimmunity (8 papers, 2013 to 2026). The occurrence of an immune reaction against the organism's own cells or tissues. "A previous report described an increased CD62Llo population among NIK KO CD25+ cells, and the presence of these activated Tregs (which also expressed increased CD69, CD45RB, and CD44) was suggested to contribute to autoimmunity." (PMID 24073289, 2013). "During the 14-day observation, the expressions of CD44 and CD49d slightly decreased on day 14 in the NS group, maybe due to autoimmunization." (PMID 27314019, 2016). "At approximately 1 year of age, CD4-ERα KO mice spontaneously showed mild autoimmunity with increased autoantibody production and CD4+CD44+CXCR5+Bcl-6+ TFH cells in the mesenteric lymph nodes and spleen." (PMID 30988419, 2019). "Because of their critical role in endogenous antigen presentation and autoimmunity in T1D16,17, cell surface expression of CD44 and MHC class I was determined in NIT-1 cells." (PMID 30718757, 2019). "In the current study, we determined that a novel class of donor-derived CD8+CD44+CD122+ Tregs (d-CD8+CD122+ Tregs) plays a crucial role in controlling autoimmunity in non-obese diabetic (NOD) mice with induced mixed chimerism." (PMID 41889910, 2026).
chondrosarcoma (8 papers, 2012 to 2023). A malignant cartilaginous matrix-producing mesenchymal neoplasm arising from the bone and soft tissue. "Together, these results indicated that downregulation of SULF1 enhances the complex formation of cMET, HGF, and CD44, consequently to increase the downstream survival signaling to promote tumorigenesis of chondrosarcoma." (PMID 36622753, 2023). "Some studies performed in chondrosarcoma cell lines have contributed to understanding the role of CD44 in these tumors and clarifying the signal transduction cascade triggered upon CD44 stimulation." (PMID 35785191, 2022). "The interaction between cMET and CD44 was clearly detected by immunoprecipitation analysis in vector control chondrosarcoma cell lines as reported, yet such interaction between cMET and CD44 was abolished in SULF1 overexpressed chondrosarcoma cell lines." (PMID 36622753, 2023). "Furthermore, while the EMT markers including Slug, MMP9, MMP2, CD44, N-Cadherin, and vimentin were suppressed by BTZ concomitant increased expression of E-Cadherin was detected in chondrosarcoma cells." (PMID 33674562, 2021). "Thus, CD44 positive and CD44v3 negative expressions were found in the chondrogenic component of dedifferentiated peripheral chondrosarcoma, whereas in secondary peripheral chondrosarcomas was detected the expression of CD44 negative− and CD44v3 positive isoforms." (PMID 35785191, 2022).
dysplasia (8 papers, 2021 to 2025). A usually neoplastic transformation of the cell, associated with altered architectural tissue patterns. "The results showed that the accuracy of CD44 and TGF-B diagnostic markers for differentiationof SCC from dysplastic leukoplakia was 0.984 (95% CI: 0.958-1.016, p< 0.001) and 0.807 (95% CI: 0.643-0.971,p< 0.01), respectively." (PMID 33681421, 2021). "Besides CD44, the study also analyzed ALDH1 expression, which proved to be an important marker for the malignant transformation of OPMD, especially in high-risk dysplasia cases." (PMID 40005368, 2025). "The study revealed that the average number of CD44-immunopositive cells was greater in normal mucosa compared to OPMD without dysplasia, as well as low-risk dysplasia, high-risk dysplasia, and OSCC." (PMID 40005368, 2025). "CD44 protein expression and spatial regulation has been observed in a dermis-based organotypic 3D culture model of oral epithelium, with an increase in expression from normal OE through to dysplasia and then carcinoma, and with CD44 expression closely associated with the basal layer." (PMID 34680271, 2021). "Five sections each from 40 histopathologically diagnosed cases of different grades of OED and 10 cases of normal oral mucosa without dysplasia were immunohistochemically stained with p16, ALDH1, CD44, SOX2, and OCT4, respectively." (PMID 34709167, 2021).
Ewing sarcoma (8 papers, 2015 to 2025). A small round cell tumor that lacks morphologic, immunohistochemical, and electron microscopic evidence of neuroectodermal differentiation. "Nevertheless, there are tumors that are CD44-dependent, CD44-weakly-dependent, or CD44-independent, such as Ewing’s sarcoma." (PMID 39851489, 2025). "While our study has provided valuable insights into the functional implications of CD44 in the context of Ewing sarcoma, it is important to acknowledge the inherent limitations associated with the in vitro models." (PMID 37511533, 2023). "We generated three Ewing sarcoma cell lines (A673/TR/CD44s, MHH-ES1/TR/CD44s, and CADO-ES1/TR/CD44s) to study the functional role of CD44 in Ewing sarcoma." (PMID 37511533, 2023). "Once these cell models were characterized, we analyzed the effect of CD44s upregulation on cell proliferation, clonogenic capability, cell migration, and invasive properties in order to determine the possible role of CD44 in Ewing sarcoma tumorigenesis." (PMID 37511533, 2023). "In consequence, it would be interesting to define the complete functional spectrum of CD44 in Ewing sarcoma, with a focus on its possible role in cell migration and invasiveness." (PMID 37511533, 2023). "CD44 was detected by immunochemistry in 14 out of 15 Ewing sarcoma tissues whose score was positive for the presence of blood lakes." (PMID 35785191, 2022). "CD44 has been reported to mediate enhanced adhesion of Ewing ́s sarcoma cells to the extracellular matrix ligand hyaluronic acid." (PMID 31810195, 2019). "Cytospin preparations of vasculogenic EW7 Ewing sarcoma cells showed a clear membranous staining for CD44." (PMID 26189059, 2015). "At this knockdown rate, diminished CD44 expression resulted in a significantly reduced migration capacity of vasculogenic Ewing sarcoma cells on hyaluronic acid." (PMID 26189059, 2015). "In Ewing sarcoma patient tissues, we found a positive correlation between CD44 expression and vasculogenic blood lake presence." (PMID 26189059, 2015). "From these results and the observation that CD44 expression is associated with vasculogenic structures and blood lakes in human Ewing sarcoma tissues, we conclude that CD44 increases aggressiveness in tumors through the process of vasculogenic mimicry." (PMID 26189059, 2015). "Collectively, CD44 was found to be expressed in 14 out of 15 Ewing sarcoma tissues scored positive for the presence of blood lakes (93% of cases, p < 0.002)." (PMID 26189059, 2015). "The mechanism potentially involved in the negative regulation of CD44 expression in Ewing sarcoma under these conditions remains unknown, but it clearly correlates with the expression levels of EWSR1::FLI1 protein." (PMID 37511533, 2023). "CD44, which interacts with hyaluronic acid (HA), commonly found in connective tissue and bone marrow, could activate the CD44-HA axis in Ewing sarcoma cells." (PMID 37511533, 2023). "Hence, we considered studying the role of CD44 as a potential driver for Ewing sarcoma progression and aggressiveness." (PMID 37511533, 2023). "Beyond this observation, the role of CD44 in the progression, metastasis, or drug resistance of Ewing sarcoma remains unclear." (PMID 35785191, 2022). "To verify our in vitro findings, we stained a set of human Ewing sarcoma tissues for CD44." (PMID 26189059, 2015). "In addition, CD44 expression was found to heavily correlate with the presence of blood lakes in tumor tissues of patients with Ewing sarcoma." (PMID 26189059, 2015). "Interestingly, the role of CD44 in Ewing sarcoma has been superficially explored." (PMID 37511533, 2023). "Thus, it is important to know what specific CD44 isoforms are present upon EWSR1::FLI1 knockdown, as this may be relevant to understanding the role of CD44 in Ewing sarcoma." (PMID 37511533, 2023). "Thus, further research is required to define the role of CD44 in Ewing sarcoma." (PMID 35785191, 2022).
Ewing sarcoma (continued). "Our data indicate that CD44 expression was upregulated upon EWSR1::FLI1 knockdown, and thus it is expressed in the EWSR1::FLI1low phenotype of Ewing sarcoma cells." (PMID 37511533, 2023). "By using the extensively studied A673/TR/shEF cell line, we showed that CD44 was dramatically upregulated upon EWSR1::FLI1 downregulation (that is, in the EWSR1::FLI1low phenotype), suggesting that CD44 is repressed by EWSR1::FLI1 in EWSR1::FLI1high Ewing sarcoma cells." (PMID 37511533, 2023). "Therefore, we next studied the differential adherence of EW7 cells to hyaluronic acid, the natural ligand of CD44, and compared it with adherence of the non-aggressive - low CD44 expressing - SIM.EW27 Ewing sarcoma cells." (PMID 26189059, 2015).
inflammatory bowel disease (8 papers, 2020 to 2025). A spectrum of small and large bowel inflammatory diseases of unknown etiology. "In inflammatory bowel disease (IBD), such as Crohn’s disease and ulcerative colitis, increased expression of CD44 variants—particularly CD44v3, CD44v6, and CD44v7—has been reported in the intestinal mucosa." (PMID 41009438, 2025). "CD44 expressed in monocytes and lymphocytes seems to play a crucial role in gastrointestinal inflammation, such as the one occurring in the context of inflammatory bowel diseases." (PMID 36010364, 2022). "Inflammatory bowel diseases (IBDs) are chronic conditions that can benefit from the combined treatment of adenosine receptor agonists and hyaluronic acid (HA), which, binding the CD44, has pro-survival effects." (PMID 33092298, 2020). "CD44 is closely related to multiple autoimmune disorders, including RA, SLE, MS, and inflammatory bowel disease (IBD)." (PMID 34484216, 2021). "Additionally, moieties (CD44, and CD99) involved in the lymphocyte and polymorphonuclear leukocytes trafficking and correlated positively with inflammatory bowel disease (IBD) disease activity, were also significantly decreased." (PMID 33330453, 2020).
ischemia (8 papers, 2012 to 2025). A hypoperfusion of the BLOOD through an organ or tissue caused by a PATHOLOGIC CONSTRICTION or obstruction of its BLOOD VESSELS, or an absence of BLOOD CIRCULATION. "Besides ischemia, also in inflammatory kidney diseases, CD44 expression is up-regulated in crescents of Bowman capsule and in injured tubular cells." (PMID 32214151, 2020). "Many of them have been previously correlated with response to ischemia (MAP 4, HPX, S100A proteins) as well as with angiogenic- and revascularization-related processes (LCN2, LRG1, CD44, MAPKAPK2)." (PMID 32143690, 2020). "In addition, many proteins potentially involved, like CD44 or matrix metalloproteinase 9 (MMP9), up-regulated in response to ischemia and decreased after CACs administration, were identified by a quantitative proteomics approach." (PMID 34572333, 2021).
ischemic stroke (8 papers, 2021 to 2025). A stroke disorder caused by obstruction of blood flow to the brain, due to thrombotic (local blood clot formation) or embolic (due to a blood clot or other material traveling from another site) event. "In particular, collagen, versican, a large extracellular matrix proteoglycan, and CD44 are more expressed in contexts showing overt neuronal damage and consequent formation of glial scar, such as ischemic stroke, compared with transient neuroinflammation induced by peripheral challenge." (PMID 40943148, 2025). "CD44, an adhesion molecule, is crucial in multiple cells and organs, with increased expression in microglia/macrophages following brain injuries, including ischemic stroke, influenced by various cytokines and molecules." (PMID 39075660, 2024). "Next, we verified whether CD44 mediated the impact of SRGN on microglial activation in ischemic stroke." (PMID 38287411, 2024). "Furthermore, CD44 and its another classical ligand, hyaluronic acid (HA), are upregulated following ischemic stroke and are correlated to enhanced inflammatory response and worse functional outcomes." (PMID 38287411, 2024). "TIMP1 unfolds protective neurovascular effects in ischemic stroke, whereas both MMP12 and osteopontin receptor CD44 may critically contribute to ischemic brain damage, suggesting that these proteins/genes may all be important therapeutic targets in ischemic stroke." (PMID 35752654, 2022). "The results demonstrated that the expression levels of FTH1, SLC40A1, NRAS, CD82, CD44, and PTPN18 were upregulated in mice with ischemic stroke following acupuncture treatment." (PMID 40552324, 2025). "Srgn knockout (KO), Cd44-KO and wild-type (WT) mice were subjected to middle cerebral artery occlusion (MCAO) to mimic ischemic stroke." (PMID 38287411, 2024). "Subsequent immunohistochemical staining in tissues from 1-week post-ischemic stroke and control marmosets, revealed an increased number of astrocytes colocalizing NogoA and either GAP43, KLF6, or CD44, consistent with the transcriptomic results." (PMID 34824275, 2021).
lung disease (8 papers, 2021 to 2025). "While CD44 supports immune cell trafficking during lung disease, it also facilitates the uptake and subsequent degradation of HA into fragments by macrophages." (PMID 41279061, 2025). "Hyaluronic acid (HA)‐decorated imatinib‐loaded liposomes (LIP‐HA44700‐Im) are developed to target CD44 positive cells for the inhalation treatment of fibrogenic lung disorders." (PMID 40837040, 2025). "However, various issues, including cellular responses to PTX3/CD44 interactions, their participation in pathogenic fibrogenesis in lung diseases and the details of PTX3/CD44‐involved molecular regulation in fibrosis, remain open questions." (PMID 36336784, 2022).